LGALS1 (galectin 1)
Description:
Lectin that binds beta-galactoside and a wide array of complex carbohydrates. Plays a role in regulating apoptosis, cell proliferation and cell differentiation. Inhibits CD45 protein phosphatase activity and therefore the dephosphorylation of Lyn kinase. Strong inducer of T-cell apoptosis. Plays a negative role in Th17 cell differentiation via activation of the receptor CD69.
Synonyms: GBP; GAL1
Tractability: Small molecule: a structure with a bound ligand is known; a high-quality ligand is known; it has a high-quality binding pocket. Antibody: UniProt places it where antibodies can reach, with high confidence; its Gene Ontology location is reachable by antibodies, with high confidence. PROTAC: ubiquitination databases record sites on it; its protein half-life has been measured; a small molecule that binds it is known. Other modalities: a drug acting on it is in phase 2 or 3 trials.
Target class: Other cytosolic protein
Gene: Protein-coding gene on chromosome 22 (37,675,636 to 37,679,805, forward strand). Ensembl gene ENSG00000100097.
Subcellular location: Secreted, extracellular space, extracellular matrix; Cytoplasm; Secreted
Subcellular location (Human Protein Atlas): Cytosol; Predicted to be secreted
Pathways (Reactome):
Metabolism of proteins: Post-translational protein phosphorylation; Regulation of Insulin-like Growth Factor (IGF) transport and uptake by Insulin-like Growth Factor Binding Proteins (IGFBPs)
Gene Ontology:
Molecular function: protein binding; receptor ligand activity; RNA binding; lactose binding; laminin binding; carbohydrate binding
Biological process: cell-cell adhesion; negative regulation of T-helper 17 cell lineage commitment; positive regulation of apoptotic process; positive regulation of canonical NF-kappaB signal transduction; positive regulation of dendritic cell differentiation; positive regulation of inflammatory response; positive regulation of viral entry into host cell; apoptotic process; regulation of apoptotic process; signal transduction
Cellular component: cytoplasm; cytosol; extracellular exosome; extracellular matrix; extracellular region; galectin complex; plasma membrane; endoplasmic reticulum lumen
Genetic constraint (gnomAD): Loss-of-function variants: 14 observed, 14.77 expected, observed/expected ratio (o/e) 0.95, 90% interval 0.62 to 1.48. The upper end of that interval is the gene's LOEUF score, 1.48, which puts it in group 6 of 6, group 1 being the genes least tolerant of losing a copy. Missense variants: 170 observed, 185.24 expected, observed/expected ratio (o/e) 0.92, 90% interval 0.81 to 1.04. Synonymous variants: 71 observed, 74.43 expected, observed/expected ratio (o/e) 0.95, 90% interval 0.79 to 1.16.
Homologues: Orthologues: chimpanzee LGALS1 (100% identical), rat Lgals1 (89% identical), mouse Lgals1 (88% identical), guinea pig LGALS1 (87% identical), pig LGALS1 (86% identical), dog LGALS1 (81% identical), rabbit LGALS1 (64% identical), tropical clawed frog lgals1 (48% identical), tropical clawed frog lgals1.4 (41% identical), tropical clawed frog lgals1.3 (39% identical), Caenorhabditis elegans F40H6.5 (30% identical), Caenorhabditis elegans lec-1 (30% identical), and 20 more. Paralogues in human: LGALS2 (41% identical), LGALS9B (33% identical), LGALS9C (33% identical), LGALS4 (33% identical), LGALS7 (33% identical), LGALS7B (33% identical), LGALS8 (33% identical), LGALS9 (33% identical), LGALSL (28% identical), LGALS3 (27% identical), GRIFIN (27% identical), LGALS12 (23% identical), and 4 more.
Diseases named in the same sentence as LGALS1 in open-access papers:
LGALS1 is named in the same sentence as 324 diseases in open-access papers, as found by Europe PMC text mining. Sharing a sentence is not in itself a finding about the gene and the disease. The quoted sentences say what the papers report.
glioma (44 papers, 2005 to 2025). A benign or malignant brain and spinal cord tumor that arises from glial cells (astrocytes, oligodendrocytes, ependymal cells). "In the same study, galectin-1 deficient glioma cells were injected into NGS (T, B, and NK cells deficient) or C57BL/6 immunocompetent mice treated with anti-asialo GM1, which depletes NK cells." (PMID 32063906, 2020). "In terms of survival, high LGALS1 expression is associated with a poor prognosis in glioma." (PMID 35632759, 2022). "High LGALS1 expression is associated with poor prognosis in glioma." (PMID 35632759, 2022). "High levels of galectin-1 in glioma have been associated with inhibiting NK cell cytotoxicity." (PMID 34209508, 2021). "Glioma cells deficient for galectin-1 showed reduced tumor growth, increased intra-tumor NK cell infiltration, and elevated expression of granzyme B when implanted into the striatum of Rag1−/− mice (which develop NK, but not T or B cells) when compared to Rag1−/− mice injected with wild-type cells." (PMID 32063906, 2020). "Galectin-1 is expressed in human gliomas and is associated with poor differentiation." (PMID 29378529, 2018). "It was unknown, however, whether the absence or presence of galectin-1 within the glioma microenvironment also causes qualitative or quantitative differences in innate and/or adaptive antitumor immune responses." (PMID 26137448, 2015). "In glioma cells, the silencing of LGALS1 and LGALS3 resulted in decreased resistance to radiotherapy, while DNA damage induced by radiation was increased." (PMID 39337581, 2024). "For example, in glioma, downregulation of LGALS1 inhibited immunosuppressive factors and reshaped the glioma immunosuppressive microenvironment by downregulating M2 macrophages and MDSCs." (PMID 38205232, 2024). "It was reported that deletion of glioma-derived as well as human pancreatic stellate cell-derived galectin-1 led to a reduced number of tumor-infiltrating MDSCs." (PMID 37047471, 2023). "GCL_TI specifically upregulates RG markers TNC, HOPX, PTPRZ1, and VIM, astrocyte markers CLU, LGALS1, as well as genes involved in migration and glioma network formation such as CD44, SPARC, and GAP43 (One peak)." (PMID 36823172, 2023). "The selective silencing of glioma-derived galectin-1 delays tumor progression and prolongs the survival of glioma-bearing mice impairing angiogenesis and the recruitment of myeloid cells as MDSCs and macrophages." (PMID 35682991, 2022). "In agreement with previous studies, our in silico analysis revealed that GBM presents significantly higher levels of LGALS1 than normal tissues, and that LGALS1 expression increases from grade II to IV gliomas." (PMID 35632759, 2022). "Recently, LGALS1 gene, coding for the galectin-1, has been included among the genes that define a glioma microenvironmental gene signature and has been identified as a key immunosuppressive gene in GB." (PMID 35682991, 2022). "Galectin-1 and Galectin-8 have been shown to participate in glioma invasion, and Galectin-1 and Galectin-3 can reportedly promote immunosuppression in glioma microenvironments." (PMID 35814469, 2022). "Galectin-1 is present on NK cells and is also known to be overexpressed in glioma, melanoma, myeloma, breast, and ovarian cancer." (PMID 34209508, 2021). "These foundational observations were based on inoculation of galectin-1 knocked-down glioma cells in both immunocompetent and immunocompromised mice." (PMID 35008740, 2021). "Silencing galectin-1 expression in the Hs683 glioma cell line impaired endothelial cell migration and tubulogenesis in vitro." (PMID 35008740, 2021). "In this context, several studies have shown that galectin-1 downregulation favors glioma cell death and increases glioma sensitivity to chemotherapeutic drugs." (PMID 35008740, 2021).
glioma (continued). "In this regard, Yamaoka and colleagues studied the effect of silencing galectin-1 expression in the rat glioma cell line 9L, and found that the growth rate, in both monolayer and soft-agar colonies, decreased when galectin-1 levels were reduced." (PMID 35008740, 2021). "LGALS1, also called galectin-1, was revealed to regulate immune responses, cancer metastasis, and cell survival in a few tumors, such as glioma, leukemia, and oral cancer." (PMID 32951492, 2020). "Recent studies have shown that patients with glioma have higher expression of some immunosuppression related genes, such as LGALS1 and IGFBP2, and blocking the expression of immune-inhibiting related genes can remodel the immunosuppression microenvironment." (PMID 33425739, 2020). "The correlation between FAM289, Galectin-1 expression and the clinical stage of gliomas was also verified in tissue samples from glioblastoma patients." (PMID 31492191, 2019). "Because radiation can induce galectin-1 expression in glioma cells, inhibition of galectin-1 expression is important for RT." (PMID 29378529, 2018). "This is consistent with the effect of exogenous Galectin-1 on other cell types including U87 glioma cells and umbilical cord blood-derived mesenchymal stem cells, for which it promotes motility." (PMID 29580262, 2018). "The data provided in this study point to a pivotal role for glioma-derived galectin-1 in the regulation of myeloid cell accumulation within the glioma microenvironment, the most abundant immune cell population in HGG." (PMID 26137448, 2015). "Both flow cytometric and pathological analysis revealed that the silencing of glioma-derived galectin-1 significantly decreased the amount of brain-infiltrating macrophages and myeloid-derived suppressor cells (MDSCs) in tumor-bearing mice." (PMID 26137448, 2015). "Galectin-1 was thus identified in this unsupervised method of analysis as a key marker of glioma invasion, while validating the novel filtering method (used to control for sample contamination) presented in this study." (PMID 22583806, 2012). "Lending credence to the utility of short-passage human-derived xenografts in modeling tumor biology, the notion of galectin-1 promoting glioma invasion is well-supported by existing data from our lab and those of others." (PMID 22583806, 2012). "Additionally, glioma cluster 2 cells expressed selectins (LGALS1 and LGALS3), integrins (ITGB1), and glycosylation targets (VIM, TIMP1, HIF1A, and CD44)." (PMID 39333557, 2024). "In addition to CTLA4, PD-1, and LAG3, other immunosuppression-related genes, like IGFBP2 and LGALS1 are highly expressed in patients with glioma." (PMID 37399661, 2023). "Moreover, the interactions of CD70, HLA-E, HVEM, FALSG, and LGALS1 expressed on the glioma cell surface and their corresponding receptors have been reported to cause T cell dysfunction, thereby enabling glioma cells to evade immune-mediated killing." (PMID 37056564, 2023). "Similarly, normal immune surveillance of NK cells is also suppressed by malignant glioma cells through the overexpression of galectin-1, and further suppresses galectin-1 and restores the normal surveillance of NK cells and eradicates glioma cells." (PMID 36560459, 2022). "Thus, galectin-1 shapes the glioma immune landscape by targeting both innate and adaptive immune compartments." (PMID 35008740, 2021). "Using a lentiviral approach to downregulate the expression of galectin-1 in GL261 glioma cells, the authors found that, 14 days after tumor inoculation, the proportion of TAMs and MDSCs significantly decreased in the TME, and this was associated with lower expression of CCL2 in tumor cells." (PMID 35008740, 2021). "In gliomas, galectin-1 also contributes to tumor angiogenesis." (PMID 35008740, 2021). "Moreover, in vivo silencing of galectin-1 in Hs683 orthotopic xenografts significantly decreased vessel density of tumors, suggesting that galectin-1 is a central player in glioma angiogenesis." (PMID 35008740, 2021).
glioma (continued). "In addition, the mRNA expression of LGALS1, which regulates the growth and metastasis of glioma cells, correlates with the malignant potential of human gliomas." (PMID 32585920, 2020). "CS nanocapsules were delivered intranasally for RNA interference (RNAi) mediated knockdown of galectin-1 in GL261 mouse glioma line, and demonstrated successful nose-to-brain transport of siRNA along with survival benefits when delivered with programmed cell death-1 (PD-1) immunotherapy in vivo." (PMID 32849207, 2020). "Our above studies have shown that FAM289 and Galectin-1 proteins are interdependent in regulating malignant behavior of glioma, so we speculated that FAM289 may also have the function to affect TMZ resistance in GBM." (PMID 31492191, 2019). "Despite evidence that galectin-1 may be involved in glioma progression in vitro, few animal studies on cancer progression have been performed, and only one human study to date reports the role of galectin-1 in glioma prognosis." (PMID 29378529, 2018). "Additionally, we demonstrated a pro-angiogenic role for galectin-1 within the glioma microenvironment." (PMID 26137448, 2015). "We explored the role of galectin-1 in the orthotopic GL261 mouse glioma model." (PMID 26137448, 2015). "Additionally, our identification of galectin-1 as a mediator of glioma invasion has been corroborated previously as detailed below." (PMID 22583806, 2012). "Our model system has identified galectin-1 as a major regulator of glioma invasion." (PMID 22583806, 2012). "In addition, ionizing radiation up-regulates galectin-1 expression in glioma cells, an effect that could limit their sensitivity to radiation therapy." (PMID 35008740, 2021). "Hence, modulation BEX2 activity could explain, at least in part, both the proangiogenic and promigratory roles of galectin-1 during glioma progression." (PMID 35008740, 2021). "Cervical cancer-derived HeLa, glioma-derived NCH125 and pancreatic carcinoma-derived BxPC3 cell lines were transfected with siRNAs targeting LGALS1 or LGALS3, or a scrambled siRNA." (PMID 35632759, 2022). "Treatment-resistant brain tumors, such as grade IV gliomas, overexpress epidermal growth factor receptor (EGFR) and galectin-1, leading to chemotherapy resistance." (PMID 32849207, 2020). "In the glioma microenvironment, FASL (CD95L), programmed cell death ligand 1/2 (PD-L1/2), galectin-1, galectin-9, HVEM, B7-H4 (B7x), and CD70/gangliosides expressed on glioma cells act as inhibitory ICMs." (PMID 32707672, 2020). "The results showed that FAM289 regulates proliferation and migration of glioma cells via ERK and NF-κB pathways, which depends on the protein-protein interaction between FAM289 and Galectin-1." (PMID 31492191, 2019). "Besides LCP1, other 16 LRGs such as LGALS1 and RPL29 should be validated in glioma progression in future studies This study has several limitations that should be acknowledged." (PMID 40740857, 2025). "It has been shown that glioma cells overexpressing galectin-1 are capable to evade NK immune surveillance, whereas the lack of galectin-1 leads to accentuated tumor-killing effects of NK cells by releasing granzyme B." (PMID 38160212, 2024). "Except for PD-1, CTLA4, and LAG3, the expression of other immunosuppression-related genes, such as LGALS1 and IGFBP2, is higher in glioma patients, and blocking the expression of immunosuppression-related genes can reshape the immunosuppressive microenvironment." (PMID 35928818, 2022). "We demonstrated that the absence of tumor-derived but not of host-derived galectin-1 significantly prolonged the survival of glioma-bearing mice as such and in combination with DC-based immunotherapy." (PMID 26137448, 2015). "Among the galectins analysed, LGALS1, LGALS3, and LGALS9 emerged as significantly upregulated in glioblastoma, consistent with prior studies identifying these molecules as key contributors to glioma progression and suggesting multifaceted roles in tumour progression and resistance mechanisms." (PMID 41516291, 2025).
glioma (continued). "The protein-protein interaction between FAM289 and Galectin-1 could activate the ERK pathway to up regulate DNMTs expression and increase stem-like properties gene expression, and thus affecting its drug sensitivity of TMZ in the treatment of gliomas." (PMID 31492191, 2019).
breast cancer (42 papers, 2012 to 2026). A primary or metastatic malignant neoplasm involving the breast. "The study revealed that the miR-22-3p/galectin-1 expression axis is associated with prognosis in breast cancer patients, with high miR-22-3p expression and low galectin-1 expression being associated with favorable prognosis." (PMID 39996781, 2025). "The direct interaction of Galectin-1 with integrin β1 causes resistance to doxorubicin in breast cancer cells." (PMID 37433225, 2023). "Galectin-1 (LGALS1) has been reported to be associated with the metastatic potential of breast cancer." (PMID 37475016, 2023). "We have identified that over-expression of BAG3, YAP1 and LGALS1 was associated with poor prognosis in HER2-positive breast cancers." (PMID 26883193, 2016). "Galectin 1 is synthesized by cancer as well as stromal cells and its overexpression in both cell types in breast cancer samples, indistinctly, was also associated with high tumour grade, a poor prognosis marker." (PMID 24229053, 2013). "Targeting Livin and/or Galectin-1 may provide a rational strategy to disrupt PD-L1-associated proliferative signaling and improve combinatorial therapeutic approaches in breast cancer." (PMID 41898602, 2026). "A member of the galectin family of proteins which modulate proliferation and cell-cell/cell-matrix interactions, upregulation of LGALS1 expression in breast cancer adjacent fibroblasts has been linked to metastasis and is altered in lymph node metastases compared to primary breast tumors." (PMID 32457901, 2020). "Indeed, targeting of galectin-1 overcomes tumor-associated immune suppression in a mouse model of breast cancer." (PMID 30930902, 2019). "Since long-term estradiol deprivation enhanced estrogen sensitivity in breast cancer, it may by suggested that soy consumption could overcomes tumor-associated-galectin-1-induced immunosuppression." (PMID 26006245, 2015). "The combination of galectin-1, -3 and -7 measurements with conventional markers has the potential to facilitate the differential diagnosis of patients with breast cancer and benign lesions." (PMID 41907605, 2026). "In contrast to the galectin-1 expression level, the mean expression level of miR-22-3p was lower in the cancer tissues of the 54 patients with breast cancer than in their normal tissues (p = 0.013)." (PMID 39996781, 2025). "Galectin-1 expression was measured using RT-PCR in 54 breast cancer tissues and normal control breast tissues." (PMID 39996781, 2025). "Our cell experiments showed that the galectin-1 expression was regulated by miR-22-3p and that miR-22-3p overexpression and galectin-1 suppression inhibited the proliferation and invasion of breast cancer cells." (PMID 39996781, 2025). "It was found that galectin-1 expression was higher in breast cancer tissues than that in normal tissues, and its overexpression was correlated with advanced stage and lymph node metastasis." (PMID 39996781, 2025). "A survival rate analysis using the KM plotter showed that the survival rate was significantly lower in the high galectin-1 expression groups of hormone receptor-positive luminal type-B breast cancer and basal-type breast cancer." (PMID 39996781, 2025). "Galectin-1 is one of several targets of miR-22-3p, and galectin-1 expression is regulated by miR-22-3p in breast cancer cells." (PMID 39996781, 2025). "In a study using mouse mammary cancer cells, the silencing of galectin-1 expression decreased immunosuppressive activity and suppressed tumor growth and lung metastasis." (PMID 39996781, 2025). "Galectin-1 suppression inhibits cell growth in mouse mammary tumor cells and in head and neck, lung, cervical, and ovarian cancers, and exogenous galectin-1 induces the proliferation of ovarian and pancreatic cancer cells." (PMID 39996781, 2025). "In breast cancer, galectin-1 is involved in the sensitivity to radiation and chemotherapy, tumor progression, and metastasis." (PMID 39996781, 2025).